KRAS (KRas proto-oncogene, GTPase)
Diseases named in the same sentence as KRAS in open-access papers (continued):
Sharing a sentence is not in itself a finding about the gene and the disease.
tumor (continued). "Glucose deprivation leads to the development of mutations in genes in the KRAS pathways in PC cells, which later reprogram the cellular metabolism and sustain unrestricted tumor growth." (PMID 29386069, 2018). "KRAS mutation in G12D, G12V or G13D was detected in the ctDNA of 43% and 35% of patients with tumours that were mutant and wild-type for these hotspot mutations, respectively, according to standard PCR-based analyses on tissue." (PMID 29362371, 2018). "Here, they used AAV/Cas9-mediated gene editing to simultaneously introduce 12 different KRAS mutations into each mouse and then used next-generation sequencing to measure the tumour burdens associated with each mutation." (PMID 30287508, 2018). "Two of these patients were confirmed to have tumours harbouring a KRAS mutation for an overall concordance between tissue and plasma of 84% (22/26)." (PMID 29362371, 2018). "Our relatively small cohort suggested that poor ECOG PS, a KRAS-mutated tumor, and elevated levels of serum LDH, WBC, and ALP are associated with poorer survival outcomes upon trifluridine/tipiracil treatment." (PMID 29204933, 2018). "In our study, KRAS was the most commonly mutated gene to be identified in both tumor tissue and ctDNA and accounted for 40.98% and 32.90% of mutations in tumor tissue and ctDNA, respectively." (PMID 29707525, 2018). "Firstly, we used KRAS mutation in tumor tissue as a baseline to evaluate its relationship with recurrence after primary tumor surgical resection." (PMID 29707525, 2018). "This suggests an evolutional disadvantage after the acquisition of KRAS mutations in later tumor evolution, providing an explanation for further tumor response in later treatment lines." (PMID 29491834, 2018). "The presence of KRAS mutations in this tumor indicates that EGFR-targeted therapy is likely to be ineffective." (PMID 29879069, 2018). "Prospectively collected plasma cfDNA of 232 patients subjected to colonoscopy was analyzed for KRAS mutations which had previously been identified in the tumor tissues of 35 patients." (PMID 29441349, 2018). "KRAS is one of the most frequently mutated genes in human tumors and its simultaneous expression with gsp is found in certain tumor types." (PMID 29544460, 2018). "It has been shown that the wild-type KRAS allele can act as a tumor suppressor exhibiting a full activated signaling pathway, and triggering potent antitumor responses." (PMID 29507677, 2018). "Most studies have employed primary tumor samples from sCRC patients to define the mutations of KRAS, NRAS, BRAF and PI3KCA genes." (PMID 30344942, 2018). "Tumours that were previously thought to be KRAS wild-type have now been also shown to have mutations in other parts of the RAS pathway indicating that this 5–7% of PDACs are still driven by the same pathway." (PMID 29329208, 2018). "Of them, 93 (46.3%) had CIMP-H and KRAS-mutation, which were equally distributed regarding sex, age and tumor location." (PMID 30188916, 2018). "Both APC and KRAS mutations synergistically promote cellular transformation and tumor growth, which is attributed to the activation of the RAS-ERK pathway via the aberrant activation of the Wnt/β-catenin signaling caused the loss of APC6–8." (PMID 30459318, 2018). "Snapback primer HRMA is a reliable, highly sensitive, high-throughput for detecting the common KRAS mutations in tumor samples obtained from cancer patients." (PMID 30406144, 2018). "On the other hand, the universal method for KRAS mutation detecting needs to be determined due to the high diversity of KRAS mutation and tumor cellularity in cancers, especially in PAAD." (PMID 30406144, 2018).
tumor (continued). "UC-associated neoplasia frequently showsTP53 or KRAS mutations, while mutations of the APC gene are rarely observed." (PMID 29652830, 2018). "The most frequently detected KRAS mutations were in codons 12 and 13 in both tumor tissue and ctDNA." (PMID 29707525, 2018). "Two KRAS variants (c.35G>A/p.G12D and 37G>T/p.G13C) identified in matched tumor-metastasis pairs were also found in both the primary tumors and brain metastasis of the current study." (PMID 29899834, 2018). "There is limited information so far for PC, where the ddPCR methodology has been used mainly for the detection of KRAS mutations in circulating tumor DNA in early-stage PC patients." (PMID 30401891, 2018). "Approximately 25–30% of NSCLC patients present KRAS mutations, which confer poor prognosis and high risk of tumor recurrence." (PMID 30514331, 2018). "Their results showed that about 45% of CRC patients with KRAS mutations in tumor tissues evinced these mutations in cfDNA." (PMID 30373199, 2018). "The presence of gene mutations in ctDNA and matched primary tumor tissue was compared, the KRAS concordance between which was 81.25%." (PMID 29707525, 2018). "In a recent study on cell-free circulating tumor DNA (cftDNA), Del Re and colleagues evaluated the appearance of KRAS mutations in EGFR positive NSCLC patients progressed after a TKI regimen." (PMID 29464099, 2018). "In this regard, mutant KRAS was first shown to promote chemokine secretion by tumor-initiated cells, thereby promoting tumor-associated inflammation." (PMID 29445180, 2018). "The reason why we used this strategy because there is approximately only 36–40% of patients with CRC have tumor-associated KRAS mutations." (PMID 29755662, 2018). "Oncogenic mutations in KRAS occur in 32% of CRC tumours and both CRC cell lines used in this study are KRAS mutants." (PMID 29930754, 2018). "In turn, NF-κB activation of KRAS-mutant tumor cells has been associated with enhanced RAS signaling, drug resistance, and stemness." (PMID 29445180, 2018). "The most frequently mutated genes across all tumor types included KRAS, PIK3CA, BRAF, EGFR, NRAS and ERBB2." (PMID 29854313, 2018). "To assess the impact of KRAS mutation on tumor glucose uptake, we examined the expression of GLUT-1 by immunohistochemistry in resected ICC specimens." (PMID 29642912, 2018). "Therapeutic resistance to EGFR inhibitors can result from intrinsic compensatory mechanisms such as KRAS mutations or from acquired resistance due to tumor heterogeneity and/or receptor cross-talk and heterodimerization." (PMID 30044378, 2018). "NF1 (Neurofibromin 1) acts as a tumor suppressor by turning off KRAS and its mutation is often mutually exclusive with KRAS, as it imposes a functional activation of the RAS pathway." (PMID 30338041, 2018). "Some factors clearly influenced the rate of engraftment: squamous histology, poor differentiation and larger tumor size favored engraftment; importantly, the engraftment was preferential for KRAS-mutated tumors, compared to EGFR-mutated tumors." (PMID 30060526, 2018). "Previous studies with PC-7 (KRASG12V/G12V) and PANC1 (KRASG12D/wt) xenografts have shown that siRNA vectors targeting KRAS codon-12 mutations can be effective in reducing tumor growth when injected intratumorally." (PMID 29851957, 2018). "KRAS locates in the chromosome 12, and encodes a P21 protein which is closely related to tumor formation, proliferation and migration." (PMID 29379053, 2018). "The single nucleotide substitution results in an activating KRAS mutation that is a well-known oncogenic mutation associated with the anchorage-independent growth of tumor cells through the acquisition of anoikis resistance in various malignancies." (PMID 30143682, 2018).
tumor (continued). "In contrast, in the CRYSTAL study, a correspondence was reported between the fraction of KRAS mutated tumor cells and cetuximab efficacy, with a benefit of cetuximab combined chemotherapy in patients with a low prevalence of KRAS mutations (0.1% to 0.5%)." (PMID 29652830, 2018). "In particular, discordance with the primary tumor occurred more frequently in lymph node metastases (95% vs 84%; p = 0.01), and concordance was lower in patients with primary KRAS-mutated tumors (95% vs. 86%; p =0.01)." (PMID 30477151, 2018). "A dominant mutated KRAS allele, promotes tumor progression by limiting the efficacy of MAPK signaling." (PMID 29507677, 2018). "The most frequently mutated genes across all tumor types included KRAS (30 patients), PIK3CA (16 patients), BRAF (6 patients), EGFR (5 patients), NRAS (4 patients), and ERBB2 (3 patients)." (PMID 29854313, 2018). "The frequency of KRAS mutation has been reported to be associated with age, gender, differentiation and tumor stage." (PMID 29423347, 2018). "Emerging mutations in the RAS/RAF/MAPK signaling pathway can be detected after disease progression in tumor biopsies from previously KRAS wild-type tumors and multiple mutations can coexist at the same time in the same sample." (PMID 34532592, 2018). "At univariate analysis, localization of primary tumor, site of metastases, KRAS (Kirsten RAt Sarcoma) oncogene mutational status, response to first-line chemotherapy, response to SRT and number of treated lesions predicted both PFS and OS." (PMID 30443292, 2018). "Median OS was 4.6 months (95% CI, 4.0–5.1) and 6.9 months (4.2–9.7) for patients with a KRAS-mutated tumor (n = 83) and KRAS-wild-type tumor (n = 53), respectively (HR, 1.67, 95% CI, 1.08–2.59; p = 0.02)." (PMID 29204933, 2018). "Investigators have reported that tumor cells with KRAS mutation exhibit enhanced glucose uptake and glycolysis to survive in severe conditions (i.e., low-glucose and hypoxia)." (PMID 29642912, 2018). "LUAD is characterized by a high frequency of tumor‐driving mutations in gene for epidermal growth factor receptor (EGFR) (10–30%) or KRAS (20–40%)." (PMID 30220105, 2018). "The key findings of the present study are that claudin-2 is expressed in CAFs in primary tumor tissue of mCRC in a manner which is linked to KRAS mutation status and progression-free survival." (PMID 29134439, 2018). "The tumor carried a KRAS mutation, and MLH-1, MSH-2, MSH-6, and PMS-2 immunostaining results were normal, suggesting microsatellite stability." (PMID 30043132, 2018). "Limited preclinical data suggest that KRAS mutational status of the tumor represents a plausible clinical link to systemic hypercoagulability in cancer patients." (PMID 29743116, 2018). "At univariate analysis, localization of primary tumor, site of metastases, KRAS mutational status, response to first-line chemotherapy, response to upfront SRT evaluated with FDG-PET and number of treated lesions had a positive prognostic power." (PMID 30443292, 2018). "As previously discussed, the lower incidence of mutations in lymph node metastases indicates that these metastases are caused by tumor clones that escape from the primary tumor in the early stages of the disease, before KRAS or other mutations occur." (PMID 30344942, 2018). "With respect to tumor tissue, the KRAS mutation rate was 40.98% (25/61), while it was 32.90% (25/76) in ctDNA." (PMID 29707525, 2018). "In the KRAS wild-type tumours, mutations in other RAS pathway genes were identified in 60% of cases, demonstrating the central importance of this pathway to PDAC development." (PMID 29329208, 2018). "For instance, EGFR mutations across different TCGA tumor types exhibit a 0.23 < GScore < 0.82 while mutations in KRAS have GScore values in the range of 0.36–0.97." (PMID 29848362, 2018). "When MSI-positive and ultramutator tumours were excluded from the Australian analysis, KRAS mutation was significantly associated with prognosis, but BRAF mutation was not." (PMID 30042065, 2018).
tumor (continued). "When the results of KRAS/BRAF tissue analysis by ddPCR were taken into account, 59 patients were found to have mutant tumours for either KRAS or BRAF (mutations being detected in 38 cases by standard PCR-based techniques while in 21 cases by ddPCR)." (PMID 29362371, 2018). "The effectiveness of KYA1797K on the inhibition of cetuximab-resistant KRAS-mutated CRC cells is shown by both in vitro and in vivo studies using the mouse xenograft tumor model generated from CRC cells harboring KRAS mutations." (PMID 30459318, 2018). "The concordance between BRAF and KRAS mutation analysis in tumor tissue and matched plasma was analyzed further." (PMID 30373199, 2018). "In the group of 62 patients with KRAS wild-type tumours, plasma mutations in G12D, G12V or G13D were identified in 22 cases (35%)." (PMID 29362371, 2018). "A significant association was found between KRAS mutations and right side colon tumor location (p=0.05), well-differentiated tumors (p=0.04) and absence of lymphovascular invasion (p=0.05)." (PMID 29844874, 2018). "The value is on the high end to show that for example in the case of the KRAS gene there was a dominant allele (A146T) and multiple other less frequent alleles likely reflecting the tumor's heterogeneity and the subclonal nature of the mutations." (PMID 30705875, 2018). "The KRAS mutation analysis showed a 96% concordance with tumor tissue and plasma cfDNA while the BRAF mutation analysis showed a 100% concordance." (PMID 30373199, 2018). "In its absence, the effects of MEK inhibitors have been studied in tumors expressing mutated BRAF and KRAS; however, they led to tumor resistance through feedback and crosstalk mechanisms within the EGFR/MAPK and EGFR/PI3K signaling pathway." (PMID 29907857, 2018). "On the other hand, subtype 3 includes tumours that can originate in serrated or adenomatous polyps, with the KRAS somatic mutation as their molecular hallmark." (PMID 30188916, 2018). "KRAS codon 12 mutations confer a more aggressive tumour phenotype with stronger transforming abilities compared with codon 13 mutations." (PMID 29973234, 2018). "Commonly mutated genes in colon cancer are APC tumor-suppressor gene, KRAS proto-oncogene, and MYC proto-oncogene." (PMID 29419804, 2018). "A total of 32,654 tumor samples identified with a KRAS G12X missense mutation were found from the database." (PMID 30199525, 2018). "Out of the three unclassified NSCLCs, one had KRAS G12A mutation, suggesting that it was ADCs since KRAS is most frequently mutated in this tumor subtype." (PMID 29368620, 2018). "PDAC is nearly invariably initiated by activating mutations in the KRAS oncogene, while additional mutations in tumor suppressor genes are accumulated in the course of PDAC progression." (PMID 30014851, 2018). "When the amino acid glycine 12 is mutated, KRAS protein acquires oncogenic properties that result in tumor cell-growth and cancer progression." (PMID 30199525, 2018). "Acquired mutations, including KRAS, can affect tumor growth due to the evolution of sub-clones that evolve through the selection of advantageous driver, neutral “passenger” or deleterious mutations." (PMID 29464099, 2018). "In case H263, the neoplasia harbored two KRAS mutations: 3 out of 5 sequenced regions were positive for the c.35G>A/G12D mutation at 5–31% frequencies, and 4 out of 5 regions were positive for the c.38G>A/p.G13D mutation at 16–34% frequencies." (PMID 30166531, 2018).
tumor (continued). "In 21% of samples sub-clonal KRAS mutations in circulating tumor DNA were detected, suggesting a potential role for selected mutations in resistance to endocrine therapy." (PMID 29739347, 2018). "In our preclinical xenograft model, the combination of both esiRNAs is more effective than the single esiRNA application to inhibit tumor growth caused by simultaneous interference with KRAS and PIK3CA expression." (PMID 30001368, 2018). "This represents a major problem in the treatment of three of the deadliest cancers, including pancreas, non-small cell lung and CRC, as KRAS mutations are associated with unfavourable prognosis in these tumor histotypes." (PMID 29534749, 2018). "In such samples, KRAS mutation detection rate by Real Time PCR SNaPshot assay was reduced to 15.8% as compared to 29.8% in FFPE specimens with >10% tumour cell or >100 tumour cells." (PMID 30076369, 2018). "More than 90% of tumors harbor KRAS mutations, which are known to increase the tumor invasive ability by reprogramming pancreatic cell metabolism and promoting stromal reaction." (PMID 29386069, 2018). "The observed cytotoxic effect of DMF was significantly higher after 72 h of treatment in tumor samples with a KRAS mutation (mean cell survival: 48.3% and 81.3% in tumours with and without KRAS mutation, respectively; p < 0.01) after DMF treatment." (PMID 29507676, 2018). "Of note, two different activating KRAS mutations (KRAS c.38G > A, KRAS c.436G > A) were identified in these tumours." (PMID 30029640, 2018). "Tumor samples were tested routinely for KRAS mutations in Hungary and Slovenia; some samples were tested in Turkey and Poland." (PMID 29523116, 2018). "KRAS mutated tumours represent a large fraction of human cancers, but the vast majority remains refractory to current clinical therapies." (PMID 28220783, 2017). "In previous studies we - and others - found a KRAS mutation when we diluted down to two tumor cells per ml blood in spiking experiments, and we have now found PANC-1 cells even at final concentrations of 1cell/ml." (PMID 28674438, 2017). "Firstly, our panel of tumours were evaluated for the most common KRAS (codon 12 and 13) and BRAF (V600E) mutations." (PMID 28931905, 2017). "In contrast, 6 patients were confirmed as KRAS mutated in tumor tissue, while the corresponding cfDNA genotyping for KRAS showed a wild type situation." (PMID 28328955, 2017). "Collectively, these results support a functional role of the FOSL1 target AURKA in KRAS-driven tumours and unveil the dual inhibition of AURKA and MEK activation as a potential strategy to treat tumours with KRAS mutations." (PMID 28220783, 2017). "The PIK3CA and KRAS mutations analyzed in this study are recognized hotspot point mutations, meaning they are overrepresented in tumor sequence databases compared to most other mutations." (PMID 28755461, 2017). "Several studies performed systematic review and meta-analysis to assess the prognostic value of EGFR and KRAS mutations in tumor tissue in NSCLC patients." (PMID 28430611, 2017). "We detected tumor-specific KRAS mutations in plasma samples from 58.5% of stage IV CRCs with known tissue KRAS mutations." (PMID 28459822, 2017). "Multivariate logistic regression analysis was conducted including all of the candidate predictors (gender, location, tumor size 0–19 mm, tumor size 20–29 mm, tumor size ≥ 60 mm, mucinous component, KRAS mutation, and BRAF mutation)." (PMID 28544821, 2017). "The combination of bisphosphonate with rapamycin facilitates autophagy and significantly inhibits KRAS mutation-mediated tumor growth." (PMID 28208579, 2017).